PRLR (prolactin receptor)
Diseases named in the same sentence as PRLR in open-access papers (continued):
Sharing a sentence is not in itself a finding about the gene and the disease.
adenoma (6 papers, 2012 to 2023). A neoplasm arising from the epithelium. "Prolactin receptor (PRLr) has been found increased in parathyroid adenoma cell surface, fact that implies prolactin role in parathormone regulation and adenoma pathogenesis." (PMID 37223014, 2023). "The prolactin receptor is expressed on many types of immune cells, and prolactin is secreted by adenoma cells which are known to have mitogenic effects on lymphocytes." (PMID 34286902, 2021). "Overall, PRLR expression was 2.4 fold reduced in adenomas and 4.8 fold reduced in adenocarcinomas compared to normal tissues." (PMID 22647582, 2012). "The highest PRLR expression levels were found in normal mammary tissue, while adenomas, and to an even higher degree adenocarcinomas, showed a significant decrease in prolactin receptor expression." (PMID 22647582, 2012). "Compared to normal tissue, PRLR mRNA was reduced 2.4 fold (p = 0.0261) in adenomas and 4.8 fold (p = 0.008) in adenocarcinomas." (PMID 22647582, 2012). "PRLR mRNA expression was significantly lower in adenocarcinomas compared to adenomas (p = 0.017)." (PMID 22647582, 2012). "In GH-, PRL- and TSH-secreting adenomas genes such as SLIT1, PRLR and miR377 were upregulated due to demethylation." (PMID 33168897, 2020).
cervical carcinoma (6 papers, 2013 to 2025). A carcinoma arising from either the exocervical squamous epithelium or the endocervical glandular epithelium. "Class I histone deacetylase inhibitor 4SC-202 exerts its anti-cervical cancer effects by targeting the prolactin receptor (PRLR) signaling pathway, thereby suppressing cancer cell proliferation and promoting cancer cell apoptosis." (PMID 40657246, 2025). "The PRLR has been found widely expressed in the cervix, ovary, and endometrium cancers compared to their healthy tissues." (PMID 34745013, 2021). "With regard to cervical cancer we reported an overexpression of PRLR and the presence of different forms in tissues derived from cervical cancer in comparison with premalignant lesions and healthy tissues." (PMID 26346346, 2015). "Recently, our research group observed a high induction of PRLR in samples of patients with cervical cancer compared with samples from patients with intraepithelial lesions." (PMID 26346346, 2015). "As can be seen, the PRLR mRNA detectable in all cervical cancer cell lines was augmented in comparison with HaCaT that expressed about 15 to 60 fold decrease." (PMID 24148306, 2013). "PRL and PRLR co-expression observed in cervical cancer cells suggests the existence of an autocrine–paracrine loop of action supporting the cell growth in cervical cancer." (PMID 24148306, 2013). "In a recent study of our investigation group we observed an increased PRLR expression in cervical cancer samples compared with intraepithelial cervical lesions (data not published)." (PMID 24148306, 2013). "In summary, we demonstrated that human cervical cancer cell lines HeLa, SiHa and C33A over-expressed multiple PRLR forms, and also produced autocrine PRL-like proteins." (PMID 24148306, 2013). "With this background information, we decided to evaluate the expression levels of PRL and PRLR and their possible participation in cell survival of cervical cancer cell lines." (PMID 24148306, 2013). "There are few studies that have focused on the analysis of PRL/PRLR in cervical cancer where the development of neoplastic lesions is influenced by the variation of the hormonal status." (PMID 24148306, 2013). "However, there are no investigations focused on the induction of antiapoptotic genes in cervical cancer in response to PRL/PRLR." (PMID 26346346, 2015). "However, few studies have reported the induction of PRL/PRLR in cervical cancer, so their role has been poorly studied." (PMID 26346346, 2015). "There are few reports that have focused on the analysis of the PRL or PRLR expression and its possible role in cervical cancer remains unknown." (PMID 24148306, 2013). "Our data suggests that PRL/PRLR signaling could act as an important survival factor for cervical cancer." (PMID 24148306, 2013). "The expression of multiple PRLR products (that might correspond to long and short PRLR forms) observed in cervical cancer cells lines suggests that the specific evaluation of the PRLR isoforms could be important for the diagnosis or treatment of the disease." (PMID 24148306, 2013). "In addition, we reported that PRL and PRLR induction is associated with cell survival, mainly by inhibition of apoptosis, but not by inducing proliferation, in cervical cancer cell lines." (PMID 26346346, 2015). "For this reason, the purpose of this study was to evaluate the signaling pathways involved in the antiapoptotic effect mediated by PRL/PRLR in cervical cancer, as well as the induction of antiapoptotic genes that could be subserving the development of the carcinogenic process." (PMID 26346346, 2015). "In addition, PRL augmented cell proliferation in HeLa cells and had a protective effect against etoposide induced apoptosis in HeLa, SiHa and C-33A, suggesting that PRL/PRLR signaling could act as an important survival factor for cervical cancer." (PMID 24148306, 2013).
cervical carcinoma (continued). "In the present study, we determined the expression levels of PRL and PRLR and the effect of PRL treatment on cell proliferation and apoptosis in HeLa, SiHa and C-33A cervical cancer cell lines." (PMID 24148306, 2013). "The aim of this study was to evaluate the expression of PRL/PRLR and the effect of PRL treatment on cell proliferation and apoptosis in cervical cancer cell lines." (PMID 24148306, 2013). "PRLR expression was assessed in cervical cancer cell lines (HeLa, SiHa and C-33A) and human non-tumorigenic keratinocytes (HaCaT) by western blot, immunocitochemistry and real time-PCR." (PMID 24148306, 2013). "To test whether PRL had an effect on the proliferation in cervical cancer cells, we cultured cells in the absence and presence of PRL, PRLR-AB or PRL-AB for 3 and 5 days." (PMID 24148306, 2013). "The results of this study demonstrate that PRLR are over-expressed at protein and mRNA levels in human cervical cancer cells compared with human non-tumorigenic keratinocytes." (PMID 24148306, 2013). "High expression of multiple PRLR forms and PRLvariants of 60–80 kDa were observed in cervical cancer cell lines compared with non-tumorigenic keratinocytes evaluated by Western blot, immunofluorecence and real time PCR." (PMID 24148306, 2013). "Hence, PRLR expression in cervical cancer has not been well documented and the roles of PRL and PRLR in tumor development are still unknown." (PMID 24148306, 2013).
endometriosis (6 papers, 2015 to 2025). The growth of functional endometrial tissue in anatomic sites outside the uterine body. "There is a possibility that increased prolactin serum levels in women with endometriosis could promote pelvic pain in these patients by dysregulating prolactin receptor expression." (PMID 39407928, 2024). "On the other hand, the authors of another study demonstrated that prolactin receptor blockade with antibodies completely inhibited endometriosis and concluded that enhanced local prolactin-mediated signalling in endometriotic lesions might contribute to the development of endometriosis." (PMID 39407928, 2024).
Hepatic steatosis (6 papers, 2017 to 2025). Steatosis is a term used to denote lipid accumulation within hepatocytes. "Moreover, the results revealed a novel association between the central nervous system and liver, whereby PRL/PRLR improved hepatic steatosis via the CD36 pathway." (PMID 33716958, 2021). "Thus, the released prolactin in mice consuming a high‐fat diet (HFD) can mitigate hepatic steatosis through its interaction with the hepatic prolactin receptor (PRLR) and by modulating the expression of CD36, a pivotal fatty acid translocase (FAT) of free fatty acid (FFA) uptake." (PMID 40586298, 2025). "Aerobic exercise intervention (EM group) notably increased PRLR, p-JAK2, and p-STAT5 levels (P < 0.01), indicating that exercise may mitigate hepatic steatosis in NAFLD mice, likely through activation of the classical PRLR-mediated JAK2/STAT5 signaling pathway in liver." (PMID 40894210, 2025). "It was also observed that PRL/PRLR could reduce stearoyl–coenzyme A desaturase 1 (SCD1) expression in various hepatic cell lines and animal models, which is the rate-limiting enzyme in monounsaturated fatty acid biosynthesis, thereby leading to the amelioration of hepatic steatosis." (PMID 36526972, 2022).
triple-negative breast carcinoma (6 papers, 2019 to 2024). An invasive breast carcinoma which is negative for expression of estrogen receptor (ER), progesterone receptor (PR), and human epidermal growth factor receptor 2 (HER2). "In xenograft models, N8-PE24 significantly enhanced the efficacy of tamoxifen and paclitaxel when treating PRLR-positive triple-negative breast cancer." (PMID 38898487, 2024). "•Systemic knockdown of the long form prolactin receptor in vivo increases survival in an aggressive, immunocompetent model of stage IV, triple negative breast cancer." (PMID 34375938, 2021). "Therapeutic intervention of the prolactin receptor pathway will likely offer novel treatment options, in particular in triple-negative breast cancer of women." (PMID 31581718, 2019). "PRLR could be highly expressed in some cases of triple-negative breast cancer (TNBC)." (PMID 38898487, 2024).
Glucose intolerance (5 papers, 2014 to 2023). Glucose intolerance (GI) can be defined as dysglycemia that comprises both prediabetes and diabetes. "Mice heterozygous for the PrlR (PrlR+/−) display a moderate glucose intolerance and decreased β-cell proliferation during gestation and serve as a model of GDM." (PMID 36983056, 2023). "Increased PRLR expression in the hypothalamus stimulates whole body insulin sensitivity, whereas reduced PRLR expression results in insulin resistance and glucose intolerance." (PMID 36213259, 2022). "This indicated that diabetic mice null for the PRLR exhibit worse glucose intolerance than diabetic wild type mice." (PMID 33746901, 2021). "The pharmacological blockade of CRHR2 signalling during pregnancy appears to reveal a transient and mild glucose intolerance in comparison to the more profound defect in glucose tolerance displayed by mutant PRLR mice." (PMID 32106091, 2020). "In both WT and PRLR−/− mice, glucose intolerance and an impairment of insulin sensitivity were observed demonstrating that the absence of PRLR does not impact the weight gain, the food intake, the adipocyte fate/differentiation and metabolic parameters." (PMID 24667351, 2014).
Insulin resistance (5 papers, 2013 to 2023). Increased resistance towards insulin, that is, diminished effectiveness of insulin in reducing blood glucose levels. "PRL and PRLR are related to fat metabolism and promote insulin resistance by activating the Janus kinase 2/signal transducer and activator of transcription 5 (JAK2/STAT5) signaling pathway and increasing triglyceride deposition." (PMID 36993818, 2023). "Increased PRLR expression in liver stimulates both liver and systemic insulin sensitivity, whereas reduced hepatic PRLR expression results in tissue and whole-body insulin resistance." (PMID 36213259, 2022). "Δ1-11-G129R-hPRL should also be tested for the inhibition of cancer cell proliferation overexpressing the prolactin receptor or for the control of blood glucose levels in individuals with insulin resistance." (PMID 33905023, 2021). "The enhanced prolactin signalling in adipocytes, highlighted through increased prolactin receptor expression during pregnancy in the current study, may contribute to the development of insulin resistance." (PMID 24236022, 2013).
pituitary tumor (5 papers, 2019 to 2023). A benign or malignant neoplasm affecting the pituitary gland. "Large-scale clinical case support is needed for the effects of drugs on ERα and PRLR protein levels in pituitary tumor tissues." (PMID 33173437, 2020). "Estrogen upregulates the prolactin receptors (PRLR) on pituitary tumor cells through ERα, so the binding of prolactin to the PRLR induces phosphorylation of ERα, leading to a cascade of molecular reactions causing DA resistance and promoting pituitary tumor enlargement and invasiveness." (PMID 36950000, 2023).
adenomyosis (4 papers, 2022 to 2025). The growth of endometrial tissue inside the muscular wall of the uterine corpus. "We further demonstrated the pathogenic effects of enhanced PRL-PRLR signaling in animal models and conducted a proof-of-concept study using an antibody targeting PRLR for the treatment of adenomyosis." (PMID 40804233, 2025). "In particular, we characterized a subcluster of epithelial cells with high ECM, enriched PRLR expression, and an expanded population in adenomyosis patients." (PMID 40804233, 2025). "Using animal models, we demonstrated that increased PRL signaling was sufficient to induce adenomyosis, while blocking the PRLR markedly ameliorated adenomyosis manifestations." (PMID 40804233, 2025). "DRD2 agonists have been shown to suppress PRL-induced adenomyosis and also have therapeutic potential for reducing pain and treating adenomyosis, likely through the promotion of the long isoform of PRLR (PRLR-L) and the inhibition of angiogenesis by DRD2." (PMID 35330066, 2022). "The expression of prolactin (PRL) and prolactin receptor (PRLR) was significantly upregulated in adenomyosis compared to normal myometrium." (PMID 35956024, 2022). "The therapeutic efficacy of HMI-115 in an animal model suggests that blocking PRLR could be a viable strategy for managing adenomyosis in humans." (PMID 40804233, 2025). "Indeed, the administration of HMI-115, a monoclonal antibody against PRLR, significantly curtailed the progression of adenomyosis in our mouse models, lowering both the incidence and severity of the condition." (PMID 40804233, 2025). "Importantly, we demonstrated that dysregulation of local PRL signaling led to the development and progression of adenomyosis, whereas inhibition of PRLR with the monoclonal antibody HMI-115 markedly ameliorated pathological manifestations." (PMID 40804233, 2025). "Moreover, adenomyotic lesions in mice with induced adenomyosis demonstrated increased PRL receptor (PRLR) expression." (PMID 35330066, 2022). "Moreover, we explored the therapeutic potential of targeting the PRLR for adenomyosis treatment." (PMID 40804233, 2025). "To rule out the involvement of other pituitary-derived factors in the pathogenesis of adenomyosis, we used HMI-115, a monoclonal antibody that targets PRLR, to specifically block PRLR-mediated signaling." (PMID 40804233, 2025). "Immunohistochemical staining revealed increased expression of PRLR in the absence of increased serum PRL levels in adenomyosis patients." (PMID 40804233, 2025).
Anxiety (4 papers, 2012 to 2016). Intense feelings of nervousness, tension, or panic often arise in response to interpersonal stresses. "For example, infusion of ovine PRL into the lateral cerebral ventricle produces anxiolytic effects, whereas down-regulation of PRLR following treatment with antisense oligonucleotide produces elevated anxiety- like behaviors." (PMID 27893788, 2016). "Intracerebroventricular administration of antisense oligonucleotides against the prolactin receptor was found to increase anxiety-related behavior in lactating rats as well as impair maternal behavior." (PMID 25689282, 2015). "One could argue that on the first day of stress expression level of PRLR is elevated along with enhanced levels of anxiety." (PMID 22291890, 2012). "In contrast, down-regulation of PRLR in the choroid plexus by antisense oligonucleotide treatment elevates ACTH secretion and anxiety-like behavior." (PMID 27893788, 2016).
diabetes (4 papers, 2021 to 2024). "Further studies confirmed that variants of the melatonin receptor 1B gene (MTNR1B) and the prolactin receptor gene (PRLR) were identified as the genetic risk factors for the comorbidity of diabetes and depression." (PMID 39611132, 2024). "However, the diabetes-induced reduction in circulating insulin levels was significantly higher in mice null for the PRLR." (PMID 33746901, 2021). "Because PRL stimulates β-cell mass and function, we sought to evaluate whether STZ-induced diabetes is aggravated in mice null for the PRLR." (PMID 33746901, 2021). "Our study confirmed these dynamics and showed that both the number of cases and the recovery from STZ-induced diabetes are worsened in the absence of the PRLR." (PMID 33746901, 2021). "Also, the survival rate throughout the 11 weeks of diabetes appeared lower in the absence of the PRLR (86% diabetic Prlr-/- mice and 96% diabetic Prlr+/+ mice survived)." (PMID 33746901, 2021). "We found that lack of PRLR signaling increases the prevalence and severity of STZ-induced diabetes by enhancing β-cell dysfunction (reduced proliferation, survival, and insulin production)." (PMID 33746901, 2021). "The expression and effect of the PRLR on alpha cells have not been described and further research is needed to elucidate whether α−cells are direct targets of PRL in diabetes." (PMID 33746901, 2021).